LGMN (legumain)
Diseases named in the same sentence as LGMN in open-access papers (continued):
Sharing a sentence is not in itself a finding about the gene and the disease.
atopic dermatitis (1 paper, 2019). "Legumain may play a role in atopic dermatitis, and there was reduced expression of this enzyme in intestines of mice given AndosanTM orally." (PMID 31581605, 2019).
cerebrovascular diseases (1 paper, 2022). "This review summarizes the current knowledge about legumain functions in health and disease, including kidney homeostasis, hematopoietic homeostasis, bone remodeling, cardiovascular and cerebrovascular diseases, fibrosis, aging and senescence, neurodegenerative diseases and cancer." (PMID 36555634, 2022).
cholangiocarcinoma (1 paper, 2023). A carcinoma that arises from the intrahepatic biliary tree (intrahepatic cholangiocarcinoma) or from the junction, or adjacent to the junction, of the right and left hepatic ducts (hilar cholangiocarcinoma). "Here, we evaluated the function of C. sinensis legumain (Cslegumain) in promoting the invasion and migration of cholangiocarcinoma cells and the mechanism involved." (PMID 36797792, 2023). "As a member of C. sinensis ESP, Cslegumain has high similarity with human legumain (Hlegumain), and whether it also plays an important role in cholangiocarcinoma deserves further investigation." (PMID 36797792, 2023). "Our findings indicated that Cslegumain showed very similar structures as those of human legumain and could promote the invasion and migration of cholangiocarcinoma cells by regulating some tumor-related molecules." (PMID 36797792, 2023).
clear cell renal cell carcinoma (1 paper, 2025). "Overall, our findings suggest that legumain secretion, induced by HIF2α, contributes to the malignant characteristics of clear cell renal cell carcinoma (ccRCC)." (PMID 39948060, 2025).
cystic fibrosis (1 paper, 2025). Autosomal recessive disorder caused by pathogenic variants in the CFTR gene (cystic fibrosis transmembrane conductance regulator), which encodes a chloride and bicarbonate channel expressed in epithelial cells, and follow the diagnosis criteria. "LGMN, is expressed in macrophages and a recent large-scale scRNA-seq study of BALF cells from the lungs of healthy and cystic fibrosis subjects found that LGMN expression was specifically pronounced in interstitial macrophages (IMs)." (PMID 40674406, 2025).
endometrial carcinoma (1 paper, 2022). A malignant tumor arising from the epithelium that lines the cavity of the uterine body. "In their very recent study, the authors investigated correlation of endometrial carcinoma to Legumain expression in human endometrium." (PMID 35813634, 2022).
endometriosis (1 paper, 2022). The growth of functional endometrial tissue in anatomic sites outside the uterine body. "reported, that a newly identified pseudogene of Legumain, derived from endometrial stroma and serum of endometriosis patients, could be a new predictive biomarker for ovarian endometriosis recurrence." (PMID 35813634, 2022).
hemophagocytic syndrome (1 paper, 2026). "Legumain knockout mice generally exhibit a normal phenotype, except for altered kidney function, hemophagocytic syndrome, and extramedullary hematopoiesis." (PMID 42087759, 2026).
Infertility (1 paper, 2022). "The deletion of C11orf94 leads to infertility in mice by affecting the expression of calcium pathway related proteins such as PDE1C, LGMN and ADD1, as well as sperm-oocyte fusion related proteins such as CRISP1, IZUMO1 and EQTN in mouse sperm." (PMID 36050562, 2022).
inflammatory bowel disease (1 paper, 2025). A spectrum of small and large bowel inflammatory diseases of unknown etiology. "When combined with the previously reported changes identified using FAIMS‐facilitated N‐terminomics, this study provides the most comprehensive list of legumain‐dependent proteome changes in the gut, highlighting its contribution to both normal gut physiology and inflammatory bowel diseases." (PMID 40970443, 2025).
injury (1 paper, 2022). Damage inflicted on the body as the direct or indirect result of an external force, with or without disruption of structural continuity. "The ischemia-induced brain injury was ameliorated in legumain-deficient mice challenged with brain acidosis, as compared to normal (wild type) mice, providing evidence for a role of legumain in the pathogenesis of ischemia-induced brain injury." (PMID 36555634, 2022).
liver cancer (1 paper, 2023). An epithelial or non-epithelial malignant neoplasm that arises from the liver. "It has been shown that protein legumain (LGMN) is overexpressed in breast, prostate, and liver cancer and that its role is significant in cancer development, progression, and invasion." (PMID 37895091, 2023).
liver fibrosis (1 paper, 2014). "We also identified several new genes, such as perilipin-3, legumain, and myocilin, which were associated with liver fibrosis." (PMID 25380136, 2014).
lymphoma (1 paper, 2022). A malignant (clonal) proliferation of B- lymphocytes or T- lymphocytes which involves the lymph nodes, bone marrow and/or extranodal sites. "Legumain expression was observed in the cytoplasm of these round cell tumors (MCT and lymphoma)." (PMID 35203212, 2022).
metastatic melanoma (1 paper, 2010). A melanoma that has spread from its primary site to another anatomic site. "In summary, we have shown that cystatin E/M acts as a regulator of proteolytic activity of legumain and suppressor of invasion in metastatic melanoma." (PMID 20074384, 2010).
multiple sclerosis (1 paper, 2021). A progressive autoimmune disorder affecting the central nervous system resulting in demyelination. "Immunohistochemistry showed that legumain expression in post-mortem multiple sclerosis brain tissue (n = 19) was significantly higher in the center and at the edge of white matter active and chronic active lesions." (PMID 33785790, 2021). "LGMN was highly upregulated in CPZ-42d and associated with protein networks known to be affected by multiple sclerosis." (PMID 33785790, 2021). "Cerebrospinal fluid levels of legumain, C1q and hemopexin were not significantly different between multiple sclerosis patients, other neurological diseases, or healthy controls." (PMID 33785790, 2021). "In order to investigate whether the levels of LGMN, C1Q (upregulated in CPZ) and HEMO (upregulated in EAE16d) were significantly affected in CSF samples from multiple sclerosis patients, a targeted LC–MS/MS PRM assay for quantification was developed." (PMID 33785790, 2021). "The proteins LGMN, HEMO and C1Q were not significantly altered in CSF from multiple sclerosis patients investigated." (PMID 33785790, 2021).
nematode infection (1 paper, 2022). "Gene expression by RT-qPCR detection shows that these B. xylophilus-specific legumain genes are expressed at the early stage of the nematode infection." (PMID 36142347, 2022).
Obesity (1 paper, 2024). Accumulation of substantial excess body fat. "Further research is needed to elucidate the precise role of LGMN in body weight regulation and obesity pathogenesis." (PMID 38331907, 2024). "Lastly, we show that overfeeding increases circulating levels of LGMN, a protease previously unexplored in the context of obesity." (PMID 38331907, 2024).
postmenopausal osteoporosis (1 paper, 2022). Metabolic disorder associated with fractures of the femoral neck, vertebrae, and distal forearm. "In contrast, legumain expression was increased during differentiation of BMSCs towards adipogenic lineage and presence of legumain in bone marrow adipocytes was inversely correlated with adjacent trabecular bone area in a cohort of patients with postmenopausal osteoporosis." (PMID 36555634, 2022).
preeclampsia (1 paper, 2025). Preeclampsia is a hypertensive disorder of pregnancy that is characterized by new-onset hypertension with proteinuria presenting after 20 weeks of gestation, and depending on mild or severe forms may initially present with severe headache, visual disturbances, and hyperreflexia. "Following confirmation of dysregulated CST6 and LGMN expression in the placenta of women with early-onset preeclampsia, we next sought to investigate circulating levels of CST6 and LGMN." (PMID 40234537, 2025). "LGMN expression was significantly reduced in placenta from patients with early-onset preeclampsia, relative to controls (P = 0.0309)." (PMID 40234537, 2025). "There was modest expression of LGMN in vCTB expression in early-onset preeclampsia and term control groups." (PMID 40234537, 2025). "We confirmed that CST6 and LGMN are significantly dysregulated in both placenta and circulation in women with preeclampsia, compared to controls." (PMID 40234537, 2025). "There was a significant increase in the CST6/LGMN ratio in patients who went on to develop preeclampsia (23.19 [IQR, 4.31–59.34], P = 0.0003), compared to those delivering at term without preeclampsia (12.09 [IQR, 3.50–72.87])." (PMID 40234537, 2025). "A significant strength of this study in the use of well characterised patient cohorts to confirm the dysregulation of CST6 and LGMN in preeclampsia." (PMID 40234537, 2025). "The performance of CST6 and LGMN either alone, or in combination as biomarkers for preeclampsia prediction after 36 weeks’ gestation was modest." (PMID 40234537, 2025). "For LGMN, we observed a decrease in LGMN mRNA expression in early-onset preeclampsia compared to preterm controls." (PMID 40234537, 2025). "The same was observed for LGMN in the control (green line, r2 = 0.0382, P = 0.3387) and preeclampsia (pink line, r2 = 0.0003, P = 0.9228) group." (PMID 40234537, 2025). "Our snRNA-seq analysis revealed similar expression profiles for both CST6 and LGMN between early-onset preeclampsia and term controls." (PMID 40234537, 2025). "This study aimed to characterise CST6 and one of its high affinity targets, Legumain (LGMN), in preeclampsia and assess its biomarker potential by measuring levels in maternal circulation." (PMID 40234537, 2025). "In this study, we sought to characterise CST6 and LGMN in preeclampsia." (PMID 40234537, 2025). "In preeclampsia, low levels of LGMN and further inhibition of LGMN by elevated levels of CST6 may disrupt placental development." (PMID 40234537, 2025). "Overall, our findings demonstrate that CST6 and LGMN are dysregulated in preeclampsia." (PMID 40234537, 2025). "In this same cohort, LGMN levels were unchanged in women with preeclampsia." (PMID 40234537, 2025). "Thus, significantly increased CST6 mRNA expression is accompanied by significantly reduced LGMN mRNA expression in placentas from women with early-onset preeclampsia." (PMID 40234537, 2025). "In this study, we aimed to characterise CST6 and LGMN in the placenta and in preeclampsia." (PMID 40234537, 2025). "Unlike CST6, LGMN mRNA expression increased with gestational age and with increasing fetal birth weight in the preeclampsia group." (PMID 40234537, 2025). "At 36 weeks’ gestation, circulating CST6 was significantly increased (P = 0.001), while LGMN was significantly decreased (P = 0.0135) in 21 pregnancies preceding diagnosis of preeclampsia at term, compared to 184 pregnancies that did not develop preeclampsia." (PMID 40234537, 2025).
trichoblastoma (1 paper, 2022). A benign hair follicle neoplasm with trichoblastic differentiation. "Epithelial-type tumors, including SCC, MGT, HGT, and trichoblastoma, had significantly higher legumain expressions (on average, 49.12%; SEM, 1.75%) compared to mesenchymal-type tumors (p = 0.0177)." (PMID 35203212, 2022).
tumor (90 papers, 2006 to 2026). "Additional proteins included in the fingerprint included LGMN, which is involved in processing of proteins for antigen presentation in the lysosomal/endosomal system and is associated with tumor development and invasion." (PMID 39739031, 2025). "High LGMN expression colocalizes with tumor-associated macrophages in the tumor microenvironment and correlates with poor prognosis." (PMID 40789452, 2025). "Together, our work reveals the role and underlying mechanism of LGMN-mediated tumor-macrophage interaction and supports the effort to develop therapeutic strategy by dually targeting tumor-macrophage symbiosis and immune checkpoints in GBM." (PMID 40131864, 2025). "Recent studies have reported that knocking out LGMN expression in TAMs, thereby generating tumor-bearing mice with LGMN deficiency, significantly inhibits tumor growth." (PMID 39065799, 2024). "LGMN overexpression has been associated with the more invasive and metastatic characteristics of tumor cells, indicating its critical role in cancer progression and spread." (PMID 38139241, 2023). "LGMN is an oncogenic protein expressed not only in malignant cells but also in tumor microenvironment cells, including tumor-associated macrophages." (PMID 38139241, 2023). "Through the integration of substrate‐specific for tumor‐associated enzyme legumain, unique capabilities of nanoSABER for imaging enzyme activity at molecular, cellular, and tissue levels in combination with machine learning models are shown." (PMID 37715297, 2023). "Selecting legumain as a representative tumor‐associated enzyme, we synthesized nanoSABER with alanine–alanine–asparagine (AAN) as the legumain recognition sequence, which can produce distinct Raman signatures upon enzymatic cleavage." (PMID 37715297, 2023). "Legumain encodes an asparaginyl endopeptidase that is highly upregulated in murine and human tumor tissues." (PMID 36297535, 2022). "The relatively limited expression of legumain in normal tissues and its overexpression in tumor-associated endothelial cells were also found in the current study." (PMID 35203212, 2022). "Legumain is not only located in the intracellular regions of tumors; it is also highly expressed on the surface of tumors and tumor-associated endothelial cells, where it is colocalized with integrins." (PMID 35203212, 2022). "One previous study reported that the expression of legumain in tumor epithelial cells is associated with the potential epithelial cell-intrinsic role of early-stage tumors in the extracellular matrix degradation that facilitates tumor progression." (PMID 35203212, 2022). "Studies in tumor condition indicate that cytosolic legumain interacts with E3 ligase TRAF6 and activates lys63-linked ubiquitination." (PMID 33431801, 2021). "Legumain expression is increased in macrophages located in tumour tissues, and this phenomenon is associated with ECM degradation and tissue invasion/metastasis." (PMID 33243972, 2020). "The substrate was susceptible to breakage by legumain enzyme overexpressed in tumor microenvironment, leading to tumor targeting of liposomes to the desired site." (PMID 30429787, 2018). "Over-expression of legumain occurs in tumor-associated macrophages and is thought to contribute to the tumor promoting inflammation associated with most malignancies." (PMID 28132643, 2017). "Legumain is a tumor-associated proteolytic enzyme (asparaginyl endopeptidase) that is expressed in kidney, placenta, and spleen and important for normal kidney function." (PMID 28002446, 2016). "Taken together, our results suggest that M2 tumour-associated macrophages affect degradation of the extracellular matrix and angiogenesis via overexpression of legumain, and therefore play an active role in the progression of DLBCL." (PMID 27464733, 2016). "High levels of the protease legumain have been detected in solid tumors and associated with increased tumor invasion and metastasis." (PMID 28002446, 2016).
tumor (continued). "An example is an isolated fraction of AndoSanTM that was found to inhibit the production in macrophages of the tumor-associated and pro-inflammatory protease, legumain." (PMID 27415795, 2016). "The intestines were examined blindly by microscopy and also stained for the tumor-associated protease, legumain." (PMID 28002446, 2016). "Our findings indicated that LGMN was overexpressed in cancer and was associated with tumor progression, deterioration, and poor prognosis in cancer." (PMID 26607955, 2015). "Legumain, an asparaginyl endopeptidase, is significantly overexpressed on tumor-associated macrophages." (PMID 23577091, 2013). "Legumain is expressed both intracellular and on the cell surface by tumor cells and tumor associated endothelial cells, where it is colocalized with integrins." (PMID 24023813, 2013). "Legumain is the only mammalian asparaginyl endopeptidase, which is overexpressed on tumor cells under hypoxic stress, a hallmark of solid tumors also expressed on tumor-associated macrophages (TAMs)." (PMID 24014113, 2013). "The expression of LGMN is elevated in various tumors and tumor-associated macrophages (TAMs)." (PMID 39065799, 2024). "In addition, LGMN expression in the normal cells has been found to be significantly low compared to that in the tumor cells or tumor-associated macrophages (TAMs)." (PMID 38980440, 2024). "Legumain up-regulation is associated with tumor invasion, proliferation, and angiogenesis." (PMID 36825203, 2023). "Furthermore, legumain can be used as a marker for cancer detection and targeting due to its expression being significantly lower in normal cells compared to tumors or tumor-associated macrophages (TAMs)." (PMID 36825203, 2023). "The targeted liposomal system (termed aLip) was characterized by activatable cell-penetrating ability by responding to a tumor-associated enzyme legumain; aLip thus could enhance tumor delivery efficiency and achieve deep intratumor penetration." (PMID 35392570, 2022). "These underlying mechanisms may explain the overexpression of legumain found in the canine tumor tissues in the current study." (PMID 35203212, 2022). "Another application of aroA deleted ST (Δdam, ΔaroA) demonstrated the suppression of tumor angiogenesis, tumor growth, and metastasis while delivering a murine MHC class I antigen epitopes of Legumain, a protein highly expressed in tumor-associated macrophage (TAM)." (PMID 36297535, 2022). "Though LGMN is highly expressed in the majority of human solid tumors and is associated with a more invasive and metastatic phenotype, the underlying mechanisms of its tumor-promoting effects have yet to be fully elucidated." (PMID 34966781, 2021). "A previous study indicated that tumor-promoting functions may be associated with the expression of LGMN 33-35." (PMID 31892854, 2020). "Moreover, legumain is significantly upregulated in tumour associated macrophages; this phenomenon is reportedly related to enhanced tumour metastasis through the activation of cathepsin, which possess collagenolytic and elastinolytic activities." (PMID 33243972, 2020). "In addition, increased legumain, a lysosomal peptidase, in tumor-associated macrophages increases CD8 T cell activity." (PMID 32655574, 2020). "Not only is legumain of interest because of its immune functions but it has also been reported to be overexpressed in several cancers and used as a target to eliminate tumor associated macrophages." (PMID 28132643, 2017). "Also, it has been documented that an ethanol-soluble fraction of Andosan inhibits the tumor-associated protease legumain in the murine macrophage-like cell line RAW 264.7." (PMID 29238712, 2017). "Moreover, legumain is found on tumor associated macrophages, which are important for tumor development and metastasis." (PMID 28002446, 2016). "Within tumors, legumain is produced by several cell types, including tumor-associated macrophages." (PMID 28002446, 2016).